GRHL3 (grainyhead like transcription factor 3)
Description:
Transcription factor playing important roles in primary neurulation and in the differentiation of stratified epithelia of both ectodermal and endodermal origin (By similarity). Binds directly to the consensus DNA sequence 5'-AACCGGTT-3' acting as an activator and repressor on distinct target genes. xhibits functional redundancy with GRHL2 in epidermal morphogenetic events and epidermal wound repair (By similarity). Exhibits functional redundancy with GRHL2 in epidermal morphogenetic events and epidermal wound repair but is essential to form the epidermal barrier with TGM3 as critical direct target gene among others. Despite being dispensable during normal epidermal homeostasis in the adulthood, is again required for barrier repair after immune-mediated epidermal damage, regulates distinct gene batteries in embryonic epidermal differentiation and adult epidermal barrier reformation after injury. Plays unique and cooperative roles with GRHL2 in establishing distinct zones of primary neurulation. Essential for spinal closure, functions cooperatively with GRHL2 in closure 2 (forebrain/midbrain boundary) and posterior neuropore closure (By similarity). Also required for proper development of the oral periderm. No genetic interaction with GRHL3, no functional cooperativity due to diverse target gene selectivity.
Synonyms: SOM; TFCP2L4; VWS2
Tractability: No criterion of Open Targets' tractability assessment is met for any kind of drug.
Gene: Protein-coding gene on chromosome 1 (24,199,558 to 24,364,482, forward strand). Ensembl gene ENSG00000158055.
Subcellular location: Nucleus
Subcellular location (Human Protein Atlas): Nucleoplasm; Actin filaments; Cytosol; Primary cilium
Gene Ontology:
Molecular function: chromatin DNA binding; DNA-binding transcription activator activity, RNA polymerase II-specific; protein binding; DNA-binding transcription factor activity, RNA polymerase II-specific; RNA polymerase II cis-regulatory region sequence-specific DNA binding; sequence-specific DNA binding; DNA-binding transcription factor activity
Biological process: positive regulation of transcription by RNA polymerase II; regulation of actin cytoskeleton organization; epidermis development; neural tube closure; regulation of transcription by RNA polymerase II; establishment of skin barrier; gene expression
Cellular component: nucleoplasm; nucleus; chromatin
Genetic constraint (gnomAD): Loss-of-function variants: 15 observed, 57.67 expected, observed/expected ratio (o/e) 0.26, 90% interval 0.17 to 0.4. The upper end of that interval is the gene's LOEUF score, 0.4, which puts it in group 1 of 6, group 1 being the genes least tolerant of losing a copy. Missense variants: 585 observed, 710.24 expected, observed/expected ratio (o/e) 0.82, 90% interval 0.77 to 0.88. Synonymous variants: 278 observed, 286.35 expected, observed/expected ratio (o/e) 0.97, 90% interval 0.88 to 1.07.
Homologues: Orthologues: chimpanzee GRHL3 (94% identical), dog GRHL3 (94% identical), macaque GRHL3 (94% identical), pig GRHL3 (94% identical), guinea pig GRHL3 (93% identical), mouse Grhl3 (91% identical), rat Grhl3 (91% identical), rabbit GRHL3 (86% identical), tropical clawed frog grhl3 (66% identical), zebrafish grhl3 (45% identical), Caenorhabditis elegans grh-1 (26% identical), Drosophila melanogaster gem (19% identical). Paralogues in human: GRHL1 (47% identical), GRHL2 (47% identical), UBP1 (22% identical), TFCP2 (21% identical), TFCP2L1 (20% identical).
Diseases named in the same sentence as GRHL3 in open-access papers:
GRHL3 is named in the same sentence as 72 diseases in open-access papers, as found by Europe PMC text mining. Sharing a sentence is not in itself a finding about the gene and the disease. The quoted sentences say what the papers report.
spina bifida (17 papers, 2010 to 2024). A congenital neural tube defect in which vertebrae are not fully formed. "Deletion of a conditional allele of Grhl3 using a mouse line expressing Cre recombinase expressed from Tfap2a regulatory elements recapitulated the spina bifida observed in constitutive Grhl3-null animals." (PMID 39296075, 2024). "In humans, mutations in GRHL3 have been identified as a major predisposing factor for developing spina bifida with several de novo and inherited variants in GRHL3 reported in patients with NTDs." (PMID 39296075, 2024). "Consistent with a potential contribution to the NTDs in these individuals, loss, diminished or excess expression of Grhl3 all cause spina bifida in mice." (PMID 37364051, 2023). "Similarities between ct mice and Grhl3 mutants include the chromosome on which the mutation is located in ct mice, and the fully penetrant spina bifida phenotype seen in Grhl3 mutants." (PMID 35269877, 2022). "The curly tail (ct) mutant is homozygous for a hypomorphic allele of the transcription factor grainyhead-like-3 (Grhl3) and exhibits spina bifida with 15–20% penetrance." (PMID 27114066, 2016). "The major ct gene, responsible for spina bifida, corresponds to a hypomorphic allele of grainyhead-like 3 (Grhl3) but the frequency of NTDs is strongly influenced by modifiers in the genetic background." (PMID 26924399, 2016). "The major ct gene corresponds to a hypomorphic allele of the transcription factor grainyhead-like-3 (Grhl3), null mutants of which display spina bifida with 100% penetrance." (PMID 23166514, 2012). "Rare mutations in GRHL3 have also been identified in individuals with spina bifida." (PMID 37364051, 2023). "Similarly, a separate study found that a GRHL3 missense mutation increased the risk of spina bifida and encephalocele phenotypes, and lastly, DNA methylation analyses revealed that hypomethylation of GRHL3 is associated with neural tube defects." (PMID 35269877, 2022). "Similarly, Grhl3-null mutants exhibited fully penetrant spina bifida, and lack of Grhl3 expression in the hindgut caused curly tail phenotype, which occurs during the final stages of neural tube closure." (PMID 32974388, 2020). "Additionally, GRHL3 mutations are also associated with non-syndromic palatal clefting and spina bifida." (PMID 31683705, 2019). "Nevertheless we cannot rule out a potential contribution of reduced Mthfd1L expression to spina bifida in the ct strain, acting to modify the Grhl3 effect, as we previously observed for a Lmnb1 variant (Deletion 18: 56909394) present in the ct genetic background." (PMID 26924399, 2016). "Deletion of Grhl3 expression in this cell population using a Tfap2a-Cre transgene recapitulates the spina bifida observed in Grhl3-null animals." (PMID 39296075, 2024). "Grainyhead-like 3 (GRHL3) is an indispensable transcription factor for neural tube closure as constitutive inactivation of the Grhl3 gene in mice leads to fully penetrant spina bifida." (PMID 39296075, 2024). "According to HGMD, variants in GRHL3 (missense/nonsense variants, splicing substitutions, and small indels) cause either VWS2, non-syndromic cleft palate, or spina bifida." (PMID 36901693, 2023). "For example, Lp/grainyhead-like transcription factor 3 (Grhl3) doubly heterozygous mutants develop severe spina bifida, while Lp/cordon-bleu WH2 repeat (Cobl) mutants exhibit exencephaly." (PMID 34842271, 2022). "GRHL3 mutations were reported in patients with VWS and human spina bifida, and polymorphisms were associated with both NSCL ± P and NSCPO phenotypes." (PMID 34307341, 2021). "While closure initiation (Closure 1) occurs successfully, the whole of subsequent spinal closure fails in Grhl3-/- embryos, generating extensive spina bifida." (PMID 29397878, 2018).
spina bifida (continued). "Deletion of Grhl3 in mouse (Grhl3−/−) results in neural tube defects, mimicking the human pathology spina bifida, as well as sporadic failed closure of the anterior neural tube, resulting in exencephaly in approximately 4 % of cases." (PMID 27756203, 2016). "Both of the Grhl3 gene knockout strains exhibit 100% spina bifida, whereas the hypomorphic ct/ct strain typically shows 15–20% spina bifida, and the +ct/+ct congenic strain does not exhibit spinal NTDs at all." (PMID 19824061, 2010). "Moreover, conditional inactivation of Tfap2c expression in Grhl3-expressing neural plate border cells also induces spina bifida." (PMID 39296075, 2024). "Furthermore, over-expression of Grhl3 driven by BAC transgenesis showed complete rescue of spina bifida in ct mice, confirming the functional relationship between Grhl3 and the curly-tail locus." (PMID 35269877, 2022). "Spinal neurulation appears to be highly dependent on Grhl3 with diminished expression, as in the curly tail (ct/ct) strain, complete loss in Grhl3-/-; or tissue-specific loss in the hindgut (this study) all causing failure of PNP closure, leading to spina bifida." (PMID 29397878, 2018). "Cranial NTDs (exencephaly) also occur in Grhl3 null embryos, but only among 2–14% unlike the 100% penetrance of spina bifida." (PMID 26924399, 2016).
van der Woude syndrome (11 papers, 2016 to 2025). Van der Woude syndrome (VWS) is a rare congenital genetic dysmorphic syndrome characterized by paramedian lower-lip fistulae, cleft lip with or without cleft palate, or isolated cleft palate. "Irf6 has been suggested to activate Grhl3 in the zebrafish periderm and mutations in Irf6 or Grhl3 are associated with neural crest defects (cleft-lip/palate) characteristic of Van der Woude syndrome." (PMID 35088714, 2022). "Mutations in human GRHL3 are associated with oral clefting leading to Van der Woude syndrome and non-syndromic clefting cases." (PMID 33093151, 2020). "Critical recent work has demonstrated that loss of GRHL3 leads to the craniofacial defect Van der Woude Syndrome (VWS), characterised by clefting of the secondary palate." (PMID 31683705, 2019). "Grainyhead-like-3 (GRHL3) was recently identified as the second gene that, when mutated, can leads to Van der Woude syndrome, which is characterized by orofacial clefts (OFC) and lower lip pits." (PMID 27459192, 2016). "GRHL3 is linked to Van der Woude Syndrome and Neural tube defects." (PMID 40625359, 2025). "As with Irf6, mutations in Grhl3 cause Van der Woude syndrome." (PMID 37169019, 2023). "GRHL3 mutations have also been reported in individuals with cleft lip and palate and individuals with syndromic (Van der Woude syndrome) and non-syndromic isolated cleft palate, consistent with GRHL3 expression in the oral ectoderm." (PMID 30189017, 2018).
squamous cell carcinoma (9 papers, 2018 to 2025). A carcinoma arising from squamous epithelial cells. "SCENIC analysis of the four SCC datasets implicated GRHL3 as a potential regulator of APOBEC3A in squamous cell carcinoma as well as in healthy epithelia, with strong correlations between GRHL3 activity and APOBEC3A expression evident across all studies (Dataset EV2)." (PMID 39548236, 2025). "In urothelial carcinomas (UC), GRHL3 is strongly expressed, whereas it is downregulated in squamous cell carcinomas (SCC)." (PMID 38429970, 2024). "In contrast, we show that in squamous cell carcinoma tissues, there is expansion of GRHL3 expression and activity to a subset of cells undergoing DNA replication and concomitant extension of APOBEC3A expression to proliferating cells." (PMID 38496447, 2024). "Two further studies defined GRHL3 as a potent tumor suppressor in human and mouse squamous cell carcinoma (SCC)." (PMID 33803949, 2021). "Expression levels of two of the examined genes – GRHL1 and GRHL3 – were significantly reduced in basal cell carcinoma (BCC) samples as well as in squamous cell carcinoma (SCC) samples, in comparison with the control healthy tissue from the same patient." (PMID 29301499, 2018). "Also, our results indicated that the Grhl1-null mice display increased susceptibility to chemically-induced skin tumorigenesis and deletion of Grhl3 in the epidermis increases the occurrence of squamous cell carcinoma (SCC) of the skin." (PMID 34570823, 2021). "In squamous cell carcinoma, GRHL3 functions as a strong tumor suppressor, where the deletion of Grhl3 in keratinocytes leads to hyper-proliferation epidermal keratinocytes that are more prone to chemical carcinogen induced spontaneous squamous cell carcinoma formation." (PMID 32974388, 2020). "Mechanistically, Grhl3 depletion in keratinocytes leads to the loss of tumor suppressor Pten expression, which induces the activation of PI3K/AKT/mTOR signaling and the oncogenic miR-21 expression, culminating in the formation of aggressive and poorly differentiated squamous cell carcinoma." (PMID 32974388, 2020). "The identification of GRHL3 as a transcription factor responsible for driving APOBEC3A expression in differentiating keratinocytes and in squamous cell carcinoma highlights the power of single-cell transcriptomics to uncover gene regulatory networks." (PMID 39548236, 2025). "In squamous cell carcinomas (SCC) of the skin, in oral SCC, head and neck SCC as well as breast cancer, GRHL3 has been demonstrated to mediate tumor‐suppressive effects." (PMID 38429970, 2024). "Reduced expression of GRHL3 in human basal cell carcinoma (BCC) and squamous cell carcinoma (SCC) of the skin has already been observed, but other GRHL genes were not investigated in those studies." (PMID 29301499, 2018).
breast carcinoma (8 papers, 2010 to 2025). "Upregulation of GRHL3 is strongly implicated in breast cancer, possibly by increasing the epithelial-mesenchymal transition." (PMID 28673325, 2017). "To address the consequences of low IRF6 and GRHL3 levels in cancer cell lines, we rescued their expression in the breast cancer cell line T47D and in the oral squamous carcinoma cell line SCC-68." (PMID 36457487, 2022). "And also some previous researchers found the repressed expression of GRHL3 in normal breast epithelial cells and indicated the protumorigenic role in breast cancer." (PMID 34888136, 2021). "Expression studies of breast cancer patients revealed high GRHL3 protein expression in early stage breast cancer which decreased with tumor progression." (PMID 33803949, 2021). "Higher expression of GRHL3 is measured in the early stages of breast cancer; however, significantly reduced expression in advanced stages of breast cancer was found." (PMID 34888136, 2021). "As reported, GRHL3 contributed to longer survival time and there was a positive correlation between GRHL3 expression and a favorable prognosis in patients with breast cancer." (PMID 34888136, 2021). "In breast cancer, high GRHL3 expression was found in the early stages while lower expression in advanced stages." (PMID 34888136, 2021). "However, in breast cancer, the expression level of GRHL3 was significantly increased and positively correlated with the degree of tumor deterioration." (PMID 33931584, 2021). "Four transcription factors (Bcl11a, Grhl3, Prox1, Sox11) activated in Brca1-/- mouse tumors and basal-like human breast cancers across multiple datasets were chosen for validation studies, and all were confirmed to be embryonic-enriched and highly expressed by some tumors." (PMID 23506684, 2013). "In the breast cancer cell line T47D, elevated IRF6 and GRHL3 did not modulate EMT marker expression." (PMID 36457487, 2022).
cleft palate (8 papers, 2016 to 2025). Cleft palate is a fissure type embryopathy that affects the soft and hard palate to varying degrees. "Disruption of periderm, as observed in Irf6-deficient or Grhl3-deficient mice, can cause abnormal oral adhesion and ultimately result in cleft palate." (PMID 40037804, 2025). "Truncating mutations in human GRHL3 cause cleft palate, while a missense variant is associated with increased risk of cleft palate at the population level." (PMID 32005677, 2020). "The ChIP-seq data also identified p63-bound regions associated with Pvrl1, Irf6, Fgfr2, Tcfap2a, Pdgfa, Sfn, Grhl3 and Jag2, mutations in which result in cleft palate." (PMID 28604778, 2017). "Similarly, Grhl3 null mice develop a low frequency of cleft palate, associated with abnormal periderm development, as well as fully penetrant spinal NTDs." (PMID 37364051, 2023). "Sharing of a missense mutation in independent SB and cleft palate cases supports the concept that GRHL3 may contribute to both defects." (PMID 30189017, 2018). "In addition, a missense variant (rs41268753) in GRHL3 confers risk for non-syndromic cleft palate cases of European ancestry." (PMID 27459192, 2016). "The aim of this study was to investigate the possible relationship between common functional variants in GRHL3 and susceptibility to NSOFC, especially cleft palate cases, in a Han Chinese population, one of the ethnic groups with the highest birth prevalence of orofacial clefting." (PMID 27459192, 2016). "Interestingly, SNP rs141193530 was reported in a recent publication describing variants of the GRHL3 gene in patients with nonsyndromic cleft lip with/without cleft palate (nsCL/P) as well as nonsyndromic cleft palate only." (PMID 29301499, 2018). "Similarly, in the current study we found that cleft palate can occur among Grhl2Axd/+; Grhl3+/TgGrhl3 fetuses (one out of two) and Grhl3TgGrhl3/TgGrhl3 over-expressing fetuses (one out of four) at E15.5, showing that increased Grhl2 is unlikely to cause CL/P via suppression of GRHL3." (PMID 37364051, 2023).
cleft lip (5 papers, 2018 to 2024). Congenital defect in the upper lip where the maxillary prominence fails to merge with the merged medial nasal prominences. "In conclusion, this review indicated the critical role of the IRF6 gene and its downstream genes (GRHL3, KLF17, and ESRP1/2) in the development of cleft lip and palate in zebrafish models." (PMID 38533046, 2024). "Taken together, our systematic review indicated the critical role of the IRF6 gene and its downstream genes (GRHL3, KLF17, and ESRP1/2) in the development of cleft lip and palate in zebrafish models." (PMID 38533046, 2024). "For example, dominant GRHL3 mutations were demonstrated to cause VWS and were associated with non-syndromic cleft-palate without cleft lip; however, there is also incompletely penetrant, as 46% individuals with mutations presented with apparently isolated CL/P and 10% were even asymptomatic." (PMID 32582293, 2020).
orofacial cleft (5 papers, 2016 to 2025). A disorder of facial skeleton that is characterized by cleft lip and/or cleft palate that result in feeding, speech and hearing problems caused by failures during development. "Numerous pathological variants within IRF6 and GRHL3 have been identified in orofacial cleft-affected individuals and expression of the two transcription factors has been found to be often dysregulated in cancers." (PMID 36457487, 2022). "We predict that differentiation human periderm is similarly controlled as genes encoding orthologs of these proteins are implicated in risk for orofacial clefting (e.g., GRHL3, KLF4, and KRT18)." (PMID 32031521, 2020). "Already, the human orthologs of four known elements of this GRN, Irf6, Grhl3, Klf17, and simple epithelium keratins, are implicated in risk for non-syndromic orofacial clefting." (PMID 32031521, 2020). "Mutations in the IRF6 and GRHL3 genes can lead to VWS, with a dysfunctional oral periderm contributing to the phenotypes of orofacial clefts in humans." (PMID 27459192, 2016). "However, whether orofacial cleft-associated IRF6 and GRHL3 variants in patients might also affect their cancer risk later in life, is not clear yet." (PMID 36457487, 2022).